TSC2 (TSC complex subunit 2)
Diseases named in the same sentence as TSC2 in open-access papers (continued):
Sharing a sentence is not in itself a finding about the gene and the disease.
hemorrhage (1 paper, 2020). Loss of blood from the vascular compartment to the exterior or into nonvascular body space as a result of rupture or severance of the blood vessels. "Despite the fact that overall prevalence of hemorrhage and CKD was too low to accurately define risk factors, in our sub-study we observed that all the three patients who had hemorrhage had TSC2 mutation." (PMID 33041968, 2020).
Hereditary breast and ovarian cancer syndrome (1 paper, 2025). An autosomal dominant inherited syndrome caused by mutations in the BRCA1 or BRCA2 genes.
hereditary renal carcinoma (1 paper, 2015). "C1orf24 was initially found as differentially expressed between two renal carcinoma cell lines, established from the same Tsc2 knockout (Eker) rat model of hereditary renal carcinoma." (PMID 26317551, 2015). "Furthermore, C1orf24 was reported to be expressed in other hereditary renal carcinoma models such as Tsc2 and Tsc1 knockout mice." (PMID 26317551, 2015).
Hodgkins lymphoma (1 paper, 2016). A heterogeneous group of malignant lymphoid neoplasms of B-cell origin characterized histologically by the presence of Hodgkin and Reed-Sternberg (HRS) cells in the vast majority of cases. "Among the 4 patients who had PR or SD>12 months, 1 patient with Hodgkin lymphoma had TSC2 loss, a molecular aberration that putatively activates the mTOR pathway." (PMID 27589687, 2016).
Hyperglycemia (1 paper, 2024). An increased concentration of glucose in the blood. "While we observed a hyperglycemia-associated decrease in body weight in βOGT-KO after 80 days of age, we observed normalization of body weight in the βOGT/TSC2-KO." (PMID 39388284, 2024).
Hypoinsulinemia (1 paper, 2021). A decreased concentration of insulin in the blood. "Adult male TSC2-KOPlacenta mice display hypoinsulinemia and maintain β cell function under HFD challenge." (PMID 34032632, 2021). "It will be important for future studies to assess mechanisms of hypoinsulinemia in female TSC2-KOPlacenta mice under HFD." (PMID 34032632, 2021). "In addition to hypoinsulinemia, it will be important to assess the contribution of extrapancreatic tissues by sophisticated clamp studies that can help explain insulin sensitivity in the female TSC2-KOPlacenta mice." (PMID 34032632, 2021).
inflammatory skin disease (1 paper, 2022). Inflammatory skin disorders covers a broad category that includes many conditions ranging in severity, from mild itching to grave medical health complications These disorders are common in people of all ages and races. "In summary, we could show that the TS complex is significantly involved in mTORC1 hyperactivation in inflammatory skin diseases, as pro-inflammatory cytokines induce the phosphorylation of TSC2 at S939, which in turn favors its dislocation from the lysosome, followed by degradation." (PMID 36139422, 2022).
influenza (1 paper, 2021). An acute viral infection of the respiratory tract, occurring in isolated cases, in epidemics, or in pandemics; it is caused by serologically different strains of viruses (influenzaviruses) designated A, B, and C, has a 3-day incubation period, and usually lasts for 3 to 10 days. "In this study, autophagy benefited the replication of influenza through the Akt/TSC2/mTOR signaling pathways." (PMID 33461581, 2021).
invasive breast carcinoma (1 paper, 2016). A carcinoma that infiltrates the breast parenchyma. "Reduced expression of TSC2 was determined in the invasive breast cancer compared to normal mammary epithelium." (PMID 27551323, 2016).
inverted urothelial papilloma (1 paper, 2023). An endophytic lesion in the urinary tract which shares several morphologic features with urothelial papilloma. "Additionally, through correlation analysis between the protein of HRAS and enriched pathways showed that HRAS protein might suppress mTOR pathway by inhibiting TSC2 ability in inverted urothelial papilloma." (PMID 37704624, 2023).
KBG syndrome (1 paper, 2024). KBG syndrome is a rare condition characterized by a typical facial dysmorphism, macrodontia of the upper central incisors, skeletal (mainly costovertebral) anomalies and developmental delay. "Short-read whole-genome sequencing combined with advanced bioinformatics analyses were successful in uncovering a de novo pericentric 87-Mb inversion with breakpoints in TSC2 and ANKRD11, which explains the TSC clinical diagnosis, and confirms a second underlying monogenic disorder, KBG syndrome." (PMID 38253421, 2024). "The inversion disrupts TSC2 and ANKRD11, resulting in dual diagnosis of TSC/KBG syndromes." (PMID 38253421, 2024).
laryngeal carcinoma (1 paper, 2021). Carcinoma that arises from the laryngeal epithelium. "This suggests that EGFR and INHBA can serve as prognostic hub genes for laryngeal cancer collectively with pRS genes (CFLAR, DAPK2, TSC2, CAPN10, MBTPS2, PEX14, FADD and ST13)." (PMID 34093817, 2021).
left ventricular hypertrophy (1 paper, 2013). Enlargement of the LEFT VENTRICLE of the heart. "Evidence from clinical and mouse samples has consistently demonstrated that TR3 is highly expressed and that TSC2 is weakly expressed in patients or mice with left ventricular hypertrophy." (PMID 23197407, 2013).
leukemia (1 paper, 2019). A malignant (clonal) hematologic disorder, involving hematopoietic stem cells and characterized by the presence of primitive or atypical myeloid or lymphoid cells in the bone marrow and the blood. "A gene set enrichment analysis (GSEA) showed that the gene expression pattern in CBAP-deficient leukemia cells was significantly correlated with signatures of TSC1/TSC2-dependent rapamycin-sensitive genes." (PMID 30266989, 2019).
liver disorder (1 paper, 2024). A disease involving the liver. "We here discover that IL-37d functions as a novel suppressor of Rheb independently of TSC2 to inhibit mTORC1 activation, thereby alleviating chronic alcohol-induced liver disorders." (PMID 38907105, 2024). "Consequently, the recombinant human IL-37d protein (rh-IL-37d) with a TAT peptide greatly improves alcohol-induced liver disorders by hindering Rheb-mTORC1 axis overactivation in a TSC2- independent manner." (PMID 38907105, 2024).
lymphatic malformation (1 paper, 2022). Primary lymphedema is caused by anatomic or functional defects in the lymphatic system, resulting in chronic swelling of body parts and lymphatic-system malformation. "We also found lymphatic malformations in the abdomen at 1–2% based on the patient’s risk factors (female sex and TSC2 mutation)." (PMID 35292049, 2022).
metabolic syndrome (1 paper, 2019). A cluster of metabolic risk factors for CARDIOVASCULAR DISEASES and TYPE 2 DIABETES MELLITUS. "In liver biopsies, two CpG sites (cg15283498-FOXO3; cg07012178-PRKAG2) were hypomethylated, whereas in subcutaneous adipose tissue from subjects with or without metabolic syndrome, cg07340599 (CREB5) and cg08779982 (TSC2) were hypomethylated." (PMID 30926763, 2019).
microcephaly (1 paper, 2021). A congenital or acquired developmental disorder in which the circumference of the head is smaller than normal for the person's age and sex. "Knockout of Raptor or mTOR in the developing brain causes microcephaly, reduced neural progenitor proliferation and postnatal lethality, while knockout of Tsc1 or Tsc2 causes macrocephaly and premature neural progenitor differentiation." (PMID 34381067, 2021).
neuroepithelial tumor (1 paper, 2022). "Patient 28 with a high-grade neuroepithelial tumor with MN1 alteration (HGNET-MN1-altered) and a TSC2 mutation was treated with everolimus with SD over twelve months." (PMID 35864412, 2022).
neuropathy (1 paper, 2021). A disorder affecting the nervous system that manifests with pain, tingling, numbness, and/or muscle weakness. "TSC2 mutations seemed more likely to have neuropathy than TSC1 in prenatal fetuses." (PMID 34513752, 2021).
obstetrical disorders (1 paper, 2017). "Nevertheless, further studies are needed to elucidate the exact role of myometrial stem cells in noncarrier TSC2 rats and whether disruption in normal stem cell proliferation may result in obstetrical disorders." (PMID 28395335, 2017).
osteoporosis (1 paper, 2025). A condition of reduced bone mass, with decreased cortical thickness and a decrease in the number and size of the trabeculae of cancellous bone (but normal chemical composition), resulting in increased fracture incidence. "Downregulation of Bglap, upregulation of Rankl and Trap, and a tendency toward Mmp9 and Tsc2 upregulation clearly proved osteoporosis development in Dex-treated animals." (PMID 41373561, 2025).
papillary adenoma (1 paper, 2017). An adenoma characterized by the presence of papillary epithelial patterns. "Tsc2+/- mice spontaneously develop various lesions in the kidneys including cysts, papillary adenomas, solid adenomas and carcinomas." (PMID 28938574, 2017). "The kidneys of adult Tsc2+/- mice developed lesions including cysts, papillary adenoma, solid adenoma and carcinoma." (PMID 28938574, 2017).
polymicrogyria (1 paper, 2025). A developmental brain abnormality characterized by an excessive amount of small convolutions on the surface of the brain and cognitive dysfunction. "Excess cortical folds or gyri have been observed in TSC2-driven MCDs, including TSC and polymicrogyria, though this phenotype has not been modeled in human organoids." (PMID 40967207, 2025).
Pompe disease (1 paper, 2017). "Modulation of TSC2‐Rheb pathway by amino acid arginine is particularly attractive since this approach can be added “risk‐free” to the current therapy in the clinical setting to combat muscle wasting in Pompe disease." (PMID 28130275, 2017).
psoriasis (1 paper, 2022). An autoimmune condition characterized by red, well-delineated plaques with silvery scales that are usually on the extensor surfaces and scalp. "To investigate whether cytokine-dependent hyperactivation of mTORC1 is regulated by the tuberous sclerosis complex, we first examined whether TSC2 can be phosphorylated by cytokines involved in the pathogenesis of psoriasis." (PMID 36139422, 2022). "We could show that both pathways are activated by cytokines, with a proven role in psoriasis, leading to TSC2 phosphorylation on S939." (PMID 36139422, 2022). "Thus, we assume that in psoriasis, inflammatory cytokines induce strong TSC2 phosphorylation, which in turn leads to its degradation." (PMID 36139422, 2022). "Under inflammatory conditions, such as in psoriasis, AKT and ERK become highly activated, leading to the phosphorylation of TSC2, which relocates from the lysosome and is targeted for degradation." (PMID 36139422, 2022). "Surprisingly, we could not find evidence for increased TSC2 phosphorylation in psoriasis patients." (PMID 36139422, 2022). "Surprisingly, increased TSC2 phosphorylation could not be detected in psoriasis patients." (PMID 36139422, 2022).
renal adenoma (1 paper, 2014). An adenoma arising from the renal cortex. "Studies on animal models show that the naturally occurring TSC2 mutations and TSC2 loss of heterozygosity (LOH) in the Eker rat leads to renal adenoma and carcinoma, some of which become malignant and metastasize to the lung, pancreas, and liver." (PMID 25360538, 2014).
renal fibrosis (1 paper, 2020). A final common manifestation of a wide variety of chronic kidney diseases characterized by glomerulosclerosis and tubulointerstitial fibrosis. "With the severity of renal fibrosis score, the protein levels of TRIM6 and the nuclear translocation of p50 increased significantly, while the protein levels of TSC1 and TSC2 decreased significantly in the kidney tissues of the patients." (PMID 33634104, 2020). "The expression of TRIM6 promoted the ubiquitination of TSC1 and TSC2, thereby activating mTORC1 and downstream processes of ER stress and EMT in renal fibrosis models." (PMID 33634104, 2020).
scoliosis (1 paper, 2021). A congenital or acquired spinal deformity characterized by lateral curvature of the spine. "These rare manifestations were more commonly observed in adults than children (66.2% vs. 22.7%), in females versus males (58.4% vs. 41.6%; except for scoliosis: 48.9% vs. 51.1%), and in those with TSC2 versus TSC1 (67.0% vs. 21.1%; except for thyroid adenoma: 42.9% vs. 57.1%)." (PMID 34229737, 2021).
serous carcinomas (1 paper, 2023). "The RAS-MAPK signaling pathway (genomic alterations of NF1 at 16% and KRAS at 12% with mutual exclusivity), the PI3K-mTOR pathway (PIK3CA at 12% and TSC2 at 8%), and certain receptor tyrosine kinases (ROS1 at 9% and ERBB2 at 8%) might be candidates for targeted therapy in serous carcinomas." (PMID 38201563, 2023).
status epilepticus (1 paper, 2023). Status epilepticus is defined as a continuous seizure lasting more than 30 min, or two or more seizures without full recovery of consciousness between any of them. "Mutations in the TSC1 and TSC2 genes have been reported as the genetic basis for the tuberous sclerosis disease complex, and TSC2 gene variation has been associated with status epilepticus in Chinese children." (PMID 37493735, 2023).
Still’s disease (1 paper, 2022). "Transcriptomic data from patients with Still’s disease suggest decreased expression of the mTORC1 inhibitors TSC1/TSC2 and an mTORC1 gene signature that strongly correlates with disease activity and treatment response." (PMID 36443301, 2022).
Thyroid adenoma (1 paper, 2021). The presence of a adenoma of the thyroid gland. "Similar distribution patterns of TSC gene mutation were noted in patients with or without rare manifestation, i.e. rate of TSC2 mutation being more than TSC1, with the exception of patients with thyroid adenoma who had a higher rate of TSC1 mutations than TSC2 (57.1% vs. 42.9%; p = 0.512)." (PMID 34229737, 2021).
tongue cancer (1 paper, 2006). A malignant neoplasm affecting the tongue. "In so doing, nine cases from among the 28 tongue cancers were identified that manifest TSC1 or TSC2 herteoduplexes upon DHPLC analysis." (PMID 16412252, 2006).
triple-negative breast carcinoma (1 paper, 2020). An invasive breast carcinoma which is negative for expression of estrogen receptor (ER), progesterone receptor (PR), and human epidermal growth factor receptor 2 (HER2).
urothelial carcinoma of the bladder (1 paper, 2021). "Cancers with higher rates of TSC1/TSC2 mutation include: urothelial carcinoma of the bladder and upper tract, with 6–10% incidence of TSC1 mutations and perivascular epithelioid cell tumors (PEComa) with up to 50% frequency of TSC2 and TSC1 mutations." (PMID 33891611, 2021).
uveal melanoma (1 paper, 2024). A melanoma derived from melanocytes of the uveal tract. "In contrast, BRAF-mutant uveal melanomas likely harbor a deformed TSC1/2 complex resulting from inactivating TSC2 phosphorylation at Ser664 by hyperactive MEK and ERK60." (PMID 39349825, 2024).
Wilms tumor (1 paper, 2022). An embryonal neoplasm characterized by the presence of epithelial, mesenchymal, and blastema components. "Thepatient with Wilms tumors had a fragment deletion of TSC1.Fifty-three patients showed TSC2 gene mutations." (PMID 35638823, 2022).
tumor (496 papers, 2006 to 2026). "TSC2 mutations in human HCC tissues have been associated with more aggressive tumor forms and higher recurrence rate." (PMID 41522204, 2026). "Functionally, ERO1α promoted proliferation, angiogenesis, and tumor growth in Tsc2-deficient cells, both in vitro and in vivo." (PMID 41226317, 2025). "TSC2 mutations or deletions are associated with numerous cancers and have been identified as critical drivers in tumor types with heightened mTOR pathway activity." (PMID 41181577, 2025). "The animal models demonstrate estrogen stimulates TSC2-deficient tumor growth by promoting neutrophil production." (PMID 40600043, 2025). "The AMPECT trial evaluated the significant anti-tumor activity of nab-sirolimus in patients with advanced or metastatic malignant PEComa carrying mutations in the TSC1/TSC2 genes or activation of the mTOR pathway." (PMID 40989692, 2025). "Genetic studies suggest that it is associated with mutations in the tumor suppressor genes TSC1 or TSC2." (PMID 40989692, 2025). "Historically, the AMPK protein was viewed as a tumor inhibitor because of its ability to inhibit the mTORC1 signaling pathway through the phosphorylation of TSC2 and RAPTOR, which are pathways that are often associated with carcinogenesis." (PMID 40063597, 2025). "A 76-year-old woman presenting with a painful soft tissue mass in the buttocks was diagnosed with malignant PEComa with local invasion and multiple distant metastases, and the tumor cells harbored a TSC2 gene mutation." (PMID 40989692, 2025). "The patient’s prognosis was poor, with indicators such as TSC2 mutation, tumor necrosis, high Ki-67 expression, and α-SMA-negative fibroblasts." (PMID 40308494, 2025). "The underlying pathophysiology of TSC revolves around mutations in the TSC1 or TSC2 genes, leading to the dysregulation of the mTORC1 pathway and resulting in abnormal cell proliferation and tumour growth." (PMID 39518472, 2024). "TSC is caused by loss-of-function mutations in the TSC1 or TSC2 genes, which act as tumor suppressor genes." (PMID 39119187, 2024). "It’s worth noting that P7, with a trunk mutation in TSC2, received the mTOR inhibitor Everolimus after the last progression, associated with tumor regression." (PMID 38448900, 2024). "The next-generation sequencing (NGS) of case 1 confirmed deletion mutations in SMARCA4, RAD51 and TSC2, and the tumor mutation burden (TMB) was 0.96 mutations/Mb." (PMID 38877473, 2024). "AMPK can inhibit mTOR signaling through direct phosphorylation of TSC2 (the tumor suppressor) and Raptor (a protein associated with mTOR regulation)." (PMID 39268468, 2024). "UL38 mediates this rigid activation of fatty acid biosynthesis via inhibition of the TSC2 tumor suppressor, the inactivation of which also causes rigid activation of fatty acid biosynthesis and sensitivity to glucose limitation." (PMID 38117060, 2024). "To evaluate the potential effect of PTEN/TSC1/TSC2 mutations and integrate the results with the differentiation state of tumor cells, we performed IHC analyses for mTORC1 activation (phospho-S6 Ser240/244)." (PMID 38775158, 2024). "Tuberous Sclerosis Complex (TSC) is caused by loss of function germline variants in the TSC1 or TSC2 tumor suppressor genes." (PMID 38373162, 2024). "As a multisystem disorder owing to loss of function of the tumor suppressor genes TSC1 or TSC2, TSC has variable expressivity." (PMID 39596632, 2024). "Pathogenic variants in TSC1 or TSC2 lead to dysregulated cell growth, tumor formation, and tumor progression." (PMID 39902087, 2024). "A strong positive feedback loop exists between E2 and tumor factors, which induces neutrophil expansion, subsequently exacerbating tumor growth and neutrophil-stimulating factor production, thereby leading to sustained tumor growth in TSC2-deficient tumors." (PMID 38877584, 2024).